INS (insulin)
Diseases named in the same sentence as INS in open-access papers (continued):
Sharing a sentence is not in itself a finding about the gene and the disease.
type 2 diabetes (continued). "Type 2 diabetes results in insulin resistant cells and this has been linked to other complications and atherosclerotic processes such as inflammation, decreased size of LDL particles, and endothelial dysfunction." (PMID 34068325, 2021). "The increase of butyrate induced by host genes can improve insulin response and reduce the risk of type 2 diabetes." (PMID 33628318, 2021). "Inhaled insulin has been associated with lower weight gain in type 2 diabetes and less hypoglycemia compared to subcutaneous insulin but generally demonstrates lower glycemic efficacy compared to subcutaneous insulin therapy." (PMID 37745178, 2021). "Insulin dysfunction and increased blood glucose levels are associated with obesity and type II diabetes." (PMID 34299638, 2021). "Multiple studies of type 2 diabetes have shown that use of insulin to manage glycemic control is an independent risk factor for DR." (PMID 34912295, 2021). "There is good evidence that foods with low GI improve overall blood glucose, reduce body serum lipids, improve insulin sensitivity reducing the risk for type 2 diabetes development and cardiovascular disease." (PMID 33673401, 2021). "Vegetables and fruits are rich in fibers and antioxidants that improve type 2 diabetes prevention by reducing the risk of weight gain and improving insulin sensitivity." (PMID 33920947, 2021). "Those normal subjects primarily insulin resistant are, therefore, at risk of developing type 2 diabetes." (PMID 33555509, 2021). "It has been documented that the TMAO-related pathway is linked to insulin sensitivity, glucose metabolism, and the high risk of type 2 diabetes." (PMID 34684645, 2021). "In reality, the interaction between deficiencies in insulin emission and insulin effect give the heterogeneous character of type 2 diabetes." (PMID 34068075, 2021). "Reducing sedentary time and engaging in even light intensity physical activity (>1.5–3 METs) can improve insulin sensitivity and reduce the risk of developing type 2 diabetes." (PMID 34770110, 2021). "And the cases of EWDR caused by insulin IT at a baseline of high-risk proliferative diabetic retinopathy (PDR) in type 2 diabetes patients were barely reported." (PMID 33607771, 2021). "Since 2005, with the advent of genome-wide association studies (GWAS), the number of genetic loci known to influence type 2 diabetes risk and/or related quantitative glycaemic measures (e.g. glucose, insulin, HbA1c levels) has surged." (PMID 34595549, 2021). "It has been shown that the use of hypoglycemic drug is associated with a fracture in patients with type 2 diabetes, and that among medications, the use of thiazolidinediones and insulin has a greater impact." (PMID 34485366, 2021). "Type 2 diabetes (T2D) is a chronic metabolic disease characterized by elevated blood glucose levels, primarily caused by impaired insulin secretion, increased hepatic glucose production, and insulin resistance." (PMID 33658058, 2021). "A separate study identified a common variant of human TFB1M (rs950994) associated with impaired insulin response, elevated glucose levels, and increased risk of type 2 diabetes." (PMID 33917098, 2021). "When type 2 diabetes is present, the deficiency in insulin sensitivity and insulin secretion is significant and comparable in both genders; insulin sensitivity is reduced when BMI increases in an equal proportion for both men and women." (PMID 34829598, 2021). "Loss of insulin sensitivity in tissues, such as fat, muscle, and liver, is the cause of Type 2 diabetes development." (PMID 34943006, 2021). "Resistance against insulin is a common phenomenon in diabetes type 2 patients that is usually associated with aberrant signaling of insulin." (PMID 33752586, 2021). "Mouse models overexpressing antioxidant enzymes have revealed that loss of ROS attenuates intracellular signaling induced by insulin, which infers a state of insulin resistance resembling type 2 diabetes." (PMID 35008532, 2021).
type 2 diabetes (continued). "The central ParaHox gene, Pdx, is the best studied due to its involvement in insulin regulation and since mutations in this gene are implicated in monogenic type 2 diabetes in humans." (PMID 34035261, 2021). "As this is predominantly associated with rising levels of obesity, it is possible that the variance in adult type 2 diabetes risk that can be explained by genes which also reduce insulin-mediated fetal growth becomes less important." (PMID 33569631, 2021). "Ingestion of proteins, including whey and soy, has been linked to increased insulin secretion among healthy adults, postmenopausal obese women and individuals with type 2 diabetes." (PMID 34657634, 2021). "In the current study, we found that the spouses were significantly associated with low insulin sensitivity, and that this contributed to an increased risk of developing type 2 diabetes." (PMID 34442147, 2021). "Date revealed a lack of knowledge regarding the cause of DM, only 181 (65.8%) knew that type 1 diabetes is insulin-dependent, and only 180 (65.5%) knew that type 2 diabetes is insulin resistant." (PMID 34632146, 2021). "A HP diet has also been shown to lead to a greater weight loss compared to a high-carbohydrate diet, along with an improvement in insulin parameters, highlighting its power to lower the risk of type 2 diabetes and cardiovascular diseases." (PMID 34959931, 2021). "Type 2 diabetes (T2D), which is caused by the body’s ineffective use of insulin, is the most common type seen in older adults." (PMID 34946417, 2021). "Type 2 diabetes in humans and rodents is associated with whole-body and EC resistance to the actions of the closely related hormones insulin and IGF-1." (PMID 34420367, 2021). "An insufficient release of insulin combined with impaired regulation of glucagon secretion is a hallmark of type-2 diabetes." (PMID 33810265, 2021). "Several pathways involved in AD pathology have been considered to depend on insulin, and type II diabetes is one of the risk factors for this disease in humans." (PMID 33924322, 2021). "The increased preference for sweet high caloric food in Dusp8 minor allele adds to earlier work on the association of SNP rs2334499 minor allele with the overall type 2 diabetes risk or the increased hypothalamic insulin resistance." (PMID 33131190, 2021). "The main causes of type 2 diabetes are dysfunction of pancreatic β-cells causing a reduction in the production of insulin or an increase in peripheral insulin resistance." (PMID 33510408, 2021). "Contrarily, current research is pointing towards a possible protective effect of alendronate on the risk of developing type 2 diabetes as well as reducing insulin consumption." (PMID 34867816, 2021). "It is characterized by absolute or relative deficiencies in insulin secretion (Type 1 diabetes) and/or insulin action (Type 2 diabetes) associated with chronic hyperglycemia and disturbances of carbohydrate, lipid and protein metabolism." (PMID 34946771, 2021). "The global rise in type 2 diabetes results from a combination of genetic predisposition with environmental assaults that negatively affect insulin action in peripheral tissues and impair pancreatic β-cell function and survival." (PMID 33419045, 2021). "In general, most relevant studies suggest that Ala92 carriers have worse glycemic control, an increased risk of type 2 diabetes, or decreased insulin sensitivity." (PMID 34660805, 2021). "Aging is associated with loss of proliferation of the insulin-secreting β-cell, a possible contributing factor to the increased prevalence of type 2 diabetes in the elderly." (PMID 34531828, 2021). "There is evidence from cohort and clinical studies of reduced all-cause mortality, lower risk of CVD, improved insulin sensitivity, and lower type 2 diabetes (T2D) risk associated with BB and specifically anthocyanin intake." (PMID 32932733, 2020).
type 2 diabetes (continued). "Many risk factors affect the development of CVD, including type 2 diabetes mellitus, obesity, resistance to insulin, high blood pressure, metabolic syndrome and high serum triglycerides levels and plasma lipid profile." (PMID 32679751, 2020). "SNPs in TCF7L2 were previously reported to be strongly associated with type-2 diabetes and this gene plays a role in the pancreatic insulin secretory response to incretins." (PMID 33303027, 2020). "This is probably linked to the decrease observed for patients with type 2 diabetes and the higher prevalence of patients with type 1 diabetes under tight control with intensive insulin therapy." (PMID 32704570, 2020). "Type 2 diabetes also greatly increased the risk of AD, and Aβ protein deposition competes with insulin for insulin receptors, causing insulin resistance." (PMID 32321934, 2020). "Resistance to these effects of insulin is a classic pathogenic feature of obesity and type 2 (non-insulin-dependent) diabetes mellitus (T2DM)." (PMID 32425738, 2020). "Type 2 diabetes (T2D), a continually growing scourge worldwide, arises from the interaction of multiple factors with genetic susceptibility in insulin sensitivity and secretion pathways to increase risk." (PMID 32754192, 2020). "We find that NRTI exposure is associated with reduced development of type 2 diabetes in people and that lamivudine inhibits inflammasome activation and improves insulin sensitivity in experimental systems." (PMID 32968070, 2020). "Alanine aminotransferase (ALAT) is elevated in most cases of non-alcohol fatty liver diseases and ALAT levels have been associated with decreased insulin sensitivity in subjects with type 2 diabetes." (PMID 32365670, 2020). "Type 2 diabetes (T2D), which is much more prevalent in the elderly, is caused by a combination of resistance to insulin action and insufficient compensatory insulin secretory response." (PMID 33147748, 2020). "Physical activity (PA) has been linked to a reduced risk of type 2 diabetes by reducing weight and improving insulin sensitivity." (PMID 32835373, 2020). "Type 2 diabetes is characterised by deficient insulin secretion from the pancreatic beta cells coinciding with impaired insulin sensitivity of tissues and organs with a major role in glucose clearance (adipose tissue, liver, muscle)." (PMID 32880688, 2020). "In accord, a recent study demonstrated that several measures of glycemic variability assessed by continuous glucose monitoring were significantly linked to glucagon-stimulated insulin secretion in Japanese patients with type 2 diabetes." (PMID 32775460, 2020). "Type II diabetes is a chronic condition characterized by high levels of glucose in the blood and is caused by a high resistance to the effects of insulin or to insufficient insulin production." (PMID 32098332, 2020). "One hallmark of both type 1 and type 2 diabetes is the loss of functional beta cell mass resulting in an insufficient release of insulin and development of hyperglycaemia." (PMID 32350565, 2020). "When this process breaks down, causing prolonged insulin resistance, the risk of developing type 2 diabetes and subsequent complications is heightened." (PMID 32595948, 2020). "BCAAs have been implicated in short- and long-term regulation of insulin secretion by pancreatic beta cells and are reported to prohibit beta cell function by inducing hypersecretion, an important hallmark of type 2 diabetes." (PMID 32880688, 2020). "Of note, lower RHI values were significantly associated with incident type 2 diabetes and with higher fasting insulin and HOMA-IR levels at follow-up in participants with initial normoglycemia." (PMID 32690629, 2020). "Loss or insufficiency of insulin producing beta cells is a causative factor in both type 1 and type 2 diabetes." (PMID 32978479, 2020). "An underlying question remains: What roles do current type 2 diabetes medications play in central insulin transport?" (PMID 32704569, 2020).
type 2 diabetes (continued). "This would help subtype different forms of insulin resistance states underlying the development of type 2 diabetes." (PMID 32925908, 2020). "Type 1 diabetes occurs as a result of insulin deficiency due to a defect in insulin-producing β-cells in the islets of Langerhans of the pancreas, while type 2 diabetes occurs as a consequence of insulin resistance/insensitivity of insulin receptors." (PMID 32244448, 2020). "Another nested case–control study found that high levels of free IGF-1 were associated with higher risk of type 2 diabetes in individuals with insulin levels above the median, but with lower risk in individuals with insulin levels below the median." (PMID 32548700, 2020). "The monophasic glucose response is related to insulin resistance, while people with more complex shapes have higher insulin sensitivity (IS) and lower risk for prediabetes and type 2 diabetes mellitus (T2DM)." (PMID 32258167, 2020). "In contrast, type 2 diabetes (T2D) arises when peripheral resistance to insulin signaling causes persistent demand for insulin secretion and eventual β-cell exhaustion." (PMID 33164744, 2020). "This brings about elevated damages on the islet and also causes a malfunction in β-cell response to metabolic stress and proinflammatory signals in insulin-resistant subjects which are the hallmark of glucose intolerance and full-blown type 2 diabetes." (PMID 32148647, 2020). "Third, the present study did not measure serum insulin, which cannot explain the mediation of insulin secretion on the association of fetal famine with type 2 diabetes." (PMID 32218356, 2020). "And epigenetic dysregulation is associated with several components that contribute to type 2 diabetes risk, including altered feeding behavior, insulin secretion, and insulin action." (PMID 32218356, 2020). "On the contrary, among patients with type 2 diabetes treated with insulin pump or multiple daily injections of insulin, metformin add-on therapy was associated with improvement in glucose fluctuation and reduced risk of hypoglycemia." (PMID 33457425, 2020). "Another advantage of stevia is linked to increased insulin sensitivity and hence, this herb can be helpful in management of type 2 diabetes (Anton, 2010 ▶)." (PMID 32257884, 2020). "Maternal early-pregnancy insulin concentrations were associated with one CpG known to be related to adult type 2 diabetes." (PMID 32894192, 2020). "The HMGCR gene, associated with lower LDL-C encoding for the target of statin (HMG-CoA reductase), has been reported to be causally associated with increased Type 2 Diabetes risk, higher plasma insulin and glucose." (PMID 31995593, 2020). "It drives the development of various metabolic disorders such as obesity and type 2 diabetes, caused by various age-related factors such as increased adiposity, decreased insulin sensitivity, and the dysfunction of pancreatic β cells." (PMID 31974316, 2020). "This cohort study examines the association of analogue compared with human insulin use with mortality and major cardiovascular events among adults with type 2 diabetes." (PMID 31977057, 2020). "Maternal early-pregnancy insulin was associated with one CpG known from a previous adult type 2 diabetes-associated study." (PMID 32894192, 2020). "Type 2 diabetes is caused by insensitivity or resistance of insulin action in the peripheral tissues." (PMID 32722262, 2020). "Our results showed that DNA methylation levels at cg06500161 of ABCG1 were positively associated with the use of statin, type 2 diabetes and related traits (fasting glucose and insulin) in FHS and WHI." (PMID 32612641, 2020). "rs7607980 is a missense variant in COBLL1 previously linked to fasting blood insulin and Type 2 diabetes." (PMID 33175840, 2020). "Type-II diabetes mellitus is complex metabolic disorder characterized by persistent hyperglycemia due to deficiency of insulin production or its resistance." (PMID 32063933, 2020).
type 2 diabetes (continued). "Type 2 diabetes is a growing global health problem and its main features are insulin resistance and relative deficiency of insulin." (PMID 32000567, 2020). "In individuals with type 2 diabetes treated with both oral glucose-lowering medication and insulin, higher HRs were observed for all-cause mortality in those who slept for shorter and longer durations." (PMID 32671413, 2020). "Infection with parasitic helminths has been reported to be beneficial for metabolic homeostasis by improving insulin sensitivity and lowering the risk for developing type 2 diabetes." (PMID 32614822, 2020). "Type 2 diabetes is characterised by a relative insulin deficiency and an impaired insulin sensitivity in certain specific target organs." (PMID 31690989, 2020). "MC1568 is another HDAC7 inhibitor that improves insulin secretion from type 2 diabetes patients and rescues β-cell dysfunction caused by HDAC7 upregulation." (PMID 33042011, 2020). "Taken together, these results demonstrate the potential application of ProINS-Tf as an INS analog for the prevention or treatment of type 2 diabetes and other INS resistance-associated diseases." (PMID 32382087, 2020). "Sedentary life style, obesity, insulin resistance or insulin dysregulations are common features associated with type II diabetes (T2D) or syndrome X (MetS) development." (PMID 32880856, 2020). "Madd, a splice variant of the insulinoma-glucagonoma clone 20 (IG20) gene, contains a single nucleotide polymorphism associated with human type 2 diabetes, and Madd knockout mice display hyperglycemia and impaired insulin secretion." (PMID 32616519, 2020). "Several reported microbial metabolites related to the gut microbiota were associated with an increased risk of incident type 2 diabetes, reducing insulin secretion and insulin sensitivity." (PMID 33224990, 2020). "Insulin (INS) resistance is the major cause of the development of type 2 diabetes (T2D), and it is often referred as a state in which a higher than normal level of INS is required to achieve the normal response." (PMID 32382087, 2020). "People with OGTTs that have a more complex shape have higher insulin sensitivity and a lower risk for prediabetes and type 2 diabetes." (PMID 32258167, 2020). "As an insulin sensitive tissue, the heart is affected by either decreases in circulating insulin or by the loss of insulin signaling that occur with type 1 or type 2 diabetes." (PMID 32817622, 2020). "Because of the largely unrestricted insulin signaling, hyperinsulinemia increases the risk of obesity, type 2 diabetes, and cardiovascular disease and decreases health span and life expectancy." (PMID 32819363, 2020). "Recently, metformin was shown to increase hepatic HSD11B1 activity in subjects with type 2 diabetes, an effect likely linked to increased insulin sensitivity." (PMID 32069218, 2020). "NAFLD has been associated with insulin-resistant, endogenous glucose production and, consequently, incident type 2 diabetes." (PMID 31713012, 2020). "Experimental and epidemiological studies have suggested a role of adiponectin to promote and maintain insulin sensitivity and normoglycemia high levels indicate a lower risk for type 2 diabetes." (PMID 31983031, 2020). "Lower circulating adiponectin levels have been observed in patients with obesity and type 2 diabetes compared with lean subjects, and have been associated with insulin sensitivity, lipid and glucose metabolism, and inflammation." (PMID 32015418, 2020). "Hyperinsulinemia and hyperleptinemia are commonly associated with insulin or leptin resistance and type 2 diabetes." (PMID 33046129, 2020). "A study including Finnish men demonstrated that CDKAL1 (rs7754840) was associated with increased risk for type 2 diabetes, likely via impairing insulin secretion." (PMID 32228543, 2020).